RNU6-1172P (RNA, U6 small nuclear 1172, pseudogene)
Gene: Small nuclear RNA gene on chromosome 8 (96,431,054 to 96,431,160, reverse strand). Ensembl gene ENSG00000202095.
Homologues: Orthologues: chimpanzee U6 (100% identical), macaque U6 (93% identical), dog U6 (81% identical), guinea pig U6 (75% identical), dog U6 (68% identical). Paralogues in human: RNU6-698P (84% identical), RNU6-744P (83% identical), RNU6-1042P (82% identical), RNU6-116P (82% identical), RNU6-1316P (82% identical), RNU6-24P (82% identical), RNU6-310P (82% identical), RNU6-658P (82% identical), RNU6-742P (82% identical), RNU6-1024P (81% identical), RNU6-1060P (81% identical), RNU6-1145P (81% identical), and 1284 more.